PGR (progesterone receptor)
Diseases named in the same sentence as PGR in open-access papers (continued):
Sharing a sentence is not in itself a finding about the gene and the disease.
ovarian carcinoma (continued). "Hence, we investigated the expression of SHRs and their clinical significance in patients with ovarian cancer and reported that the expression of the GR modifies the role of the progesterone receptor (PR) and affects the androgen receptor (AR)." (PMID 36969037, 2023). "In addition, metastatic ovarian lesions in breast cancer sometimes mimic the clinical and histological features of primary ovarian cancer and even lose the characteristic oestrogen receptor (ER) and progesterone receptor (PR) expression levels." (PMID 37958607, 2023). "Studies have demonstrated differential associations between the risk factors of ovarian cancer and α-ER and progesterone receptor (PR) status, while no previous research has observed associations of ovarian cancer risk factors with β-ER expression." (PMID 37809638, 2023). "This protective effect of progesterone may be partly due to the PGR-mediated suppression of progesterone receptor membrane component-1, which enhances the sensitivity of ovarian cancer cells to platinum-based chemotherapy." (PMID 37569592, 2023). "Moreover, NRF2 can regulate ERα and PGR expressions in ovarian cancer cells, playing a pivotal role in cell response to oestrogen and progesterone." (PMID 35453348, 2022). "Interestingly, NRF2 silencing induces an increase in ERα and PGR mRNA expressions in OVCAR3 cell lines, confirming a role of NRF2 in regulating ERα and PGR expression in ovarian cancer cell lines." (PMID 35453348, 2022). "A putative direct action of gonadal steroids on ovarian carcinogenesis has been suggested, which was supported by findings of mRNA transcripts and translated proteins of Estrogen receptor (ER) and Progesterone receptor (PgR) in both normal ovarian tissue and malignant ovarian tumors." (PMID 30791364, 2019). "Progesterone receptor (PR) and ER expression are reported to be associated with improved ovarian cancer survival, independent of clinical prognostic factors, but these associations have not been consistently repeated." (PMID 30326857, 2018). "First, the study shows that the expression of progesterone receptor is related to a favorable outcome of ovarian cancer, suggesting progesterone receptor may be a potential prognostic marker for ovarian cancers." (PMID 28415663, 2017). "There were three stratified subgroups about source regions of included studies, a pooled HR was 0.69 (n = 16, 95% CI = 0.55 to 0.88, P = 0.002, I2 = 73.4%) in European population, indicating that progesterone receptor positivity exerted favorable influence on OS among these ovarian cancer patients." (PMID 28415663, 2017). "Multiple in vitro studies have shown that an increased progesterone receptor expression could promote the progesterone-induced inhibition of DNA synthesis, cell division, proliferation and apoptosis in ovarian cancer cells." (PMID 28415663, 2017). "In this study, we systematically evaluated the prognostic value of progesterone receptor expression in 5685 ovarian cancer patients from 28 different studies and demonstrated that the expression of progesterone receptor was an indicator of a favorable prognosis for ovarian cancer patients." (PMID 28415663, 2017). "Progesterone receptor expression was linked to a better OS and DFS/PFS/RFS in unclassified ovarian cancers, while progesterone receptor expression was related to neither OS nor DFS/PFS/RFS in serous type of cancers." (PMID 28415663, 2017). "With regard to different detection methods of progesterone receptor in ovarian cancer, it was found that progesterone receptor expression was associated with a favorable OS of ovarian cancer in immunohistochemical staining group (n = 23, HR = 0.88, 95% CI = 0.79 to 0.96, P = 0.007, I2 = 71.5%)." (PMID 28415663, 2017). "However, the correlation between the expression of progesterone receptor and prognosis of ovarian cancer remains controversial." (PMID 28415663, 2017).
ovarian carcinoma (continued). "The protective effects of progesterone could be mediated by the nuclear progesterone receptor (n-Pr), which is gradually lost with increasing ovarian cancer malignancy." (PMID 26916548, 2016). "In order to further verify the pro-apoptotic effect of ATRA combined with Tamoxifen on ovarian cancer cells at the molecular level, the effects of different ATRA concentrations on genes related to ERα expression, such as PGR, PS2 and c-Myc were counted." (PMID 38714534, 2024). "For ovarian cancer patients, the CARIS MI ProfileTM reflexively includes mismatch repair (MMR), estrogen receptor (ER), and progesterone receptor (PR) testing." (PMID 35453890, 2022). "We analyzed the relationship between the expression of progesterone receptor and DFS/PFS/RFS among ovarian cancer patients." (PMID 28415663, 2017). "We conclude that progesterone acts via the progesterone receptor to modulate ADAMTS 1 and 4 levels in ovarian cancer cell lines." (PMID 26916548, 2016). "In contrast to the chemerin protein data from IHC, mRNA levels of the RARRES2 gene in ovarian cancer were not correlated with PGR, ESR2, ESRRA, ESRRB, ESRRG, nor CEACAM5 after analysis of both patient collectives on the mentioned platforms (p > 0.05 for all)." (PMID 36900088, 2023). "Progesterone’s protective effect may be attributed to PGR’s suppression of progesterone receptor membrane component-1 (PGRMC1), which increases the sensitivity of ovarian cancer cells to platinum-based chemotherapy." (PMID 37569592, 2023). "Our present observations on the P4 receptor expression pattern in CRC are consistent with the recently reported marginal expression of PGR, with low expression levels of mPRβ, mPRγ, and PGRMC2, and abundant expression levels of PGRMC1 in high-grade human ovarian cancer." (PMID 37894441, 2023). "In addition, the expression of PGR decreases and PGRMC1 increases with ovarian cancer progression and as a result the ratio of PGRMC1 to PGR dramatically increases with the stage of ovarian cancer." (PMID 34885064, 2021). "Finally, we performed the sub-group analysis only based on progesterone receptor expression and ovarian cancer with OS or DFS/PFS/RFS, due to the lack of effective data." (PMID 28415663, 2017). "Moreover, progesterone receptor immunopositivity was observed in the majority of borderline tumors, whereas a large percentage (93%) of malignant ovarian tumors stained negative for progesterone receptor." (PMID 28415663, 2017). "Although the progesterone receptor is not well-established as a therapeutic target in HGSOC, mifepristone (RU486), a progesterone receptor antagonist, was demonstrated to have a response rate of 26.5% in cisplatin- and paclitaxel-resistant ovarian cancer." (PMID 36430718, 2022). "However, progesterone receptor was not identified as a DFS/PFS/RFS prognostic predictor (n = 2, HR = 0.91, 95% CI = 0.61 to 1.36, P = 0.651) in ovarian cancer when other detection methods were used." (PMID 28415663, 2017).
meningioma (44 papers, 2006 to 2026). A generally slow growing tumor attached to the dura mater. "The presence of the progesterone receptor (PR) is considered a favorable prognostic indicator for meningioma, as PR status is inversely associated with tumor grade, recurrence rates, and the mitotic index." (PMID 40113789, 2025). "Compared with commonly positive in Grade I meningiomas and used as a risk predictive factor, progesterone receptor (PR) are used to be a diagnostic marker for higher grade meningioma." (PMID 36438949, 2022). "A recent review on PIK3CA‐mutated meningiomas underscores that a subset of these tumors, particularly those with non‐NF2 mutations, exhibit estrogen and progesterone receptor positivity and respond aberrantly to hormonal exposure via PIK3CA pathway activation." (PMID 41031251, 2025). "The progesterone receptor (PR) plays a significant role in the development and progression of meningioma." (PMID 40231270, 2025). "Grade I meningiomas exhibit the highest levels of progesterone receptor expression, whereas grades II and III demonstrate progressively lower expression levels." (PMID 41327755, 2025). "Immunohistochemical staining for meningioma-specific markers, such as the progesterone receptor, confirmed similar expression patterns to parental tumors." (PMID 39941893, 2025). "The progesterone receptor (PR) is an important biomarker in meningiomas, influencing tumor growth, prognosis, and potential treatment options." (PMID 40231270, 2025). "Further, these meningiomas have been observed to more often be progesterone receptor-positive and more often found on the skull base, a location that has been found to more often have sites of PI3KCA mutations." (PMID 39409982, 2024). "There is evidence that meningiomas which have developed during exposure to cyproterone acetate exhibit different progesterone receptor patterns than other meningiomas." (PMID 39409982, 2024). "MPA acts by binding to the progesterone receptor of the hypothalamus, and this receptor has been found to be important in the pathophysiology of meningiomas." (PMID 39409982, 2024). "The literature on progesterone receptor points toward a less frequent expression of progesterone receptors in higher-graded meningiomas." (PMID 38023177, 2023). "Conversely, meningiomas with high progesterone receptor expression are less likely to recur, and supratentorial NSBMs tend to have less progesterone receptor expression than skull base meningiomas." (PMID 36497370, 2022). "Evidence suggests that low-grade meningiomas have higher levels of progesterone receptor expression in comparison with malignant meningiomas." (PMID 36530973, 2022). "The progesterone receptor (PR) is variably expressed in most meningiomas and was found to have prognostic significance." (PMID 34336636, 2021). "Examination of the samples at the pathology department revealed the tumor was positive for epithelial membrane antigen (EMA), S-100 and progesterone receptor (PR) which was consistent with diagnosis of meningioma." (PMID 33578608, 2021). "Up to 88% of meningiomas are progesterone receptor positive, 40% are estrogen receptor positive, and 39% are positive for androgen receptors." (PMID 34359779, 2021). "Oestrogen also has been implicated in melanoma and papillary thyroid cancer development whereas progesterone appears to play a role in meningiomas, leading to trials with mifepristone, the progesterone receptor antagonist." (PMID 32183012, 2020). "We cannot evaluate the exact estrogen receptor and progesterone receptor statuses to further correlate the hormone effects on the possible relationship between tamoxifen and meningioma, either." (PMID 31249531, 2019). "PTX3 level was negatively correlated with tumor volume and progesterone receptor level in our cohort which supports the argument that the gene can act as a tumor suppressor for meningioma." (PMID 28327132, 2017).
meningioma (continued). "We are reporting a case of cerebral infarction due to a sphenoid wing meningothelial meningioma (with progesterone receptor positivity) leading to an occlusion of the middle cerebral artery (MCA) in a 30-year-old right-handed woman (1 month after childbirth)." (PMID 24198989, 2013). "Immunohistochemistry staining showed that tumor cells of meningioma were strongly immunoreactive for vimentin, epithelial membrane antigen, and progesterone receptor." (PMID 23198201, 2012). "The presence of progesterone receptor expression in meningioma tissue has been observed in previous pathology studies." (PMID 16759391, 2006). "However, progesterone receptor expression is higher and can be found in 70-80% of meningiomas compared to the estrogen receptor expression, which can be lower than 10%." (PMID 40642710, 2025). "Out of a total of 13 variables preselected for this study, previous meningioma surgery, Simpson grade, progesterone receptor staining as well as presence of necrosis and patternless growth on histopathological analysis of 378 patients were included into the final model." (PMID 38023177, 2023). "One possibility is the progesterone-receptor independent growth of meningiomas in male patients." (PMID 33674888, 2021). "Data of 30 reviewed studies on the progesterone receptor expression in meningiomas." (PMID 34336636, 2021). "The antiproliferative effect of RU486 in normal or neoplastic cells appears to be complex; its action was found to be dependent on the interaction with progesterone receptor in cultured human meningioma cells or with glucocorticoid receptor, in prostate cancer cells." (PMID 33053110, 2020). "The diagnosis of meningioma can be confirmed by immunohistochemical stains since most meningiomas express EMA (epithelial membrane antigen,), progesterone receptor, and vimentin." (PMID 36230612, 2022). "The meningioma cells were stained strongly with epithelial membrane antigen (EMA) and progesterone receptor (PR)." (PMID 32423480, 2020). "Several studies have reported that PgR positivity is a prognostic predictor in conventional meningiomas, but the role of PgR in CCM has not yet been fully investigated and requires further research." (PMID 40663004, 2025). "58-83% of meningiomas express progesterone receptor as opposed to 0-8 % expressing estrogen receptor." (PMID 30617760, 2020). "In contrast, meningioma cells showed prominent nuclear immunoreaction for progesterone receptor and remained negative for GATA3." (PMID 30343679, 2018). "In most progesterone receptor positive tissues, estrogens modulate the presence of PR but this seems not to be the case for meningiomas." (PMID 26146614, 2015). "However, it had been shown that the progesterone receptor is only expressed on non-dividing meningioma cells." (PMID 33674888, 2021). "The occurrence of meningioma and tamoxifen use might plausibly be connected; hormonal factors have been proven to be involved in the development of meningioma, and approximately 70% of meningiomas show progesterone receptor expression whereas approximately 30% show estrogen receptor expression." (PMID 31249531, 2019).
leiomyoma (43 papers, 2012 to 2026). A well-circumscribed benign smooth muscle neoplasm characterized by the presence of spindle cells with cigar-shaped nuclei, interlacing fascicles, and a whorled pattern. "Mifepristone, also known as RU486, is the original progesterone receptor modulator, which demonstrated improvement of leiomyomata-associated quality of life and reduction in fibroid size." (PMID 38524211, 2024). "Estradiol causes an increase in progesterone receptor expression and supports progesterone action in growth of leiomyomas." (PMID 33546154, 2021). "New drugs for medical management of uterine fibroids such as selective progesterone receptor modulators and oral GnRH antagonists are associated with a 50–60% reduction in fibroid size, but larger fibroids tend to persist and may continue to cause symptoms." (PMID 33914296, 2021). "Preoperative imaging and biopsy of perihepatic lesions confirmed benign leiomyomas with estrogen and progesterone receptor (PR) positivity." (PMID 42257061, 2026). "This interpretation is supported by the coexistence of other leiomyomas and progesterone receptor positivity." (PMID 40978684, 2025). "The growth of a leiomyoma correlates with the progesterone receptor content and the proportion of smooth muscle in a leiomyoma." (PMID 38524211, 2024). "ESR1, estrogen receptor 2 (ESR2) and PGR were significantly up-regulated in endothelial cells of leiomyoma compared to pseudocapsule." (PMID 37215998, 2023). "Here, both snRNA-seq and ST results showed that ESR1 and PGR were expressed higher in leiomyoma than these in pseudocapsule and myometrium." (PMID 37215998, 2023). "Although the exact mechanism of how ovarian steroid hormones drive the tumorigenesis of leiomyoma is still unclear, estrogen receptors and progesterone receptor are indispensable during this process." (PMID 37215998, 2023). "In postmenopausal leiomyomas, the expression of progesterone receptor was higher than that in the adjacent myometrium." (PMID 35974345, 2022). "Progesterone modulators include mifepristone, which is a selective progesterone receptor modulator (SPRM) that works to decrease the size of leiomyomas." (PMID 36703761, 2022). "Ulipristal acetate (UPA), a selective progesterone receptor modulator, is used for the treatment of uterine fibroids and selectively inhibits the proliferation and inflammation of leiomyoma cells." (PMID 35036597, 2022). "The results suggest that estrogen and progesterone can directly stimulate leiomyoma cell proliferation based on the expression of PGR and ESR1 in the proliferating cells." (PMID 35203298, 2022). "This group has further reported that the PGR gene locus and its genome-wide cistrome are hypermethylated in leiomyoma stem cells, repressing the expression of genes for progesterone-mediated leiomyoma stem cell differentiation." (PMID 35203298, 2022). "The exact mechanism of selective progesterone receptor modulator action in leiomyoma still challenges researchers." (PMID 34442017, 2021). "Estradiol (E2) can induce the expression of the progesterone receptor (PR) to directly affect human leiomyoma cells." (PMID 34123993, 2021). "Selective progesterone receptor modulators (SPRM) have been offered as effective medical therapy for leiomyomas, with minimal side effects and promising long-term results." (PMID 29312996, 2017). "Selective progesterone receptor modulators (SPRMs) have emerged as a valuable treatment option for hormone dependent conditions like uterine fibroids, which have a major impact on women’s quality of life." (PMID 27138351, 2016). "Leiomyoma expresses both estrogen and progesterone receptors, with estradiol able to induce progesterone receptor expression and support progesterone action on leiomyoma tissue." (PMID 26783463, 2015). "On immunohistochemistry, tumor cells were positive for smooth muscle actin (SMA) as well as for estrogen and progesterone receptor (ER/PR), confirming the diagnosis of leiomyoma." (PMID 25032139, 2014).